JAK2 (Janus kinase 2)
Diseases named in the same sentence as JAK2 in open-access papers (continued):
Sharing a sentence is not in itself a finding about the gene and the disease.
cancer (continued). "Janus kinase 2 (JAK2) is a protein that contributes to drug-resistant cancer and its inhibition can increase cytotoxicity of chemotherapy in MDR cells and increase the efficacy of anticancer drugs." (PMID 35562984, 2022). "The mutational analysis determined that genes previously identified in cancers were most commonly observed in the profiled patients with mutations in NRAS, KRAS, JAK2, and CREBBP." (PMID 36497424, 2022). "The different structures of JAK2 inhibitors can allow for their use in clinics as alternative backup inhibitors for resistant cancer cells." (PMID 35562984, 2022). "Activation of IL-6/JAK2/STAT3 pathway is closely associated with EMT and stem cell-like features, ultimately leading to poor outcomes in various human cancer patients." (PMID 36591515, 2022). "Activation of IL-6/JAK2/STAT3 pathway is closely associated with EMT and stem cell-like features, ultimately leading to poor prognosis in patients with various cancers." (PMID 36591515, 2022). "The top four mutated genes in pediatric cancers were NRAS (1.8%), KRAS (0.9%), JAK2 (0.3%), and CREBBP (0.3%), highlighting that these genes should be analyzed further to assess the clinical significance of these mutations." (PMID 36497424, 2022). "The JAK2 inhibitor lestaurtinib was screened by the Genomics of Cancer Drug Sensitivity Project (GDSC) analysis." (PMID 35646925, 2022). "JAK2 inhibitors have been shown to increase drug-cytotoxicity in P-gp-overexpressing drug-resistant cancer cells through P-gp inhibitory activity." (PMID 35562984, 2022). "Andrographolide is known to inhibit the actions of STAT3, JAK1, and JAK2 phosphorylation in human cancer cells." (PMID 35682652, 2022). "In PCa, JAK2/STAT3 can regulate the malignant phenotype of cancer cells through rewiring metabolic pathways." (PMID 35818076, 2022). "In JAK family, JAK2 has become an important target for cancer therapy due to its role in cell growth and survival." (PMID 36591515, 2022). "We have previously shown that STIP1 stabilizes the protein tyrosine kinase JAK2 in cancer cells via HSP90 binding." (PMID 35269562, 2022). "Accumulating evidence indicated that JAK2/STAT3 was closely correlated with cancer metastasis and progression 14-15." (PMID 35813296, 2022). "Momelotinib (CYT387), a JAK1 and JAK2 inhibitor, also showed strong anti-cancer activity by significantly reducing MM proliferation in preclinical results." (PMID 35503759, 2022). "It targets certain oncogenes, such as AEG-1/MTDH, PDK1, YWHAZ/14-3-3ζ, YAP and JAK2, in multiple types of carcinomas." (PMID 35205648, 2022). "Nifuroxazide acts as an effective inhibitor of the STAT3 signaling pathway by reducing Jak2 autophosphorylation in cancer cells." (PMID 34833950, 2021). "The inhibition of JAK2 signaling activates mitochondrial-dependent apoptotic pathways to induce cancer cell apoptosis." (PMID 33959183, 2021). "Taken together, these data unequivocally confirmed that CAFs-secreted IL-6 induced LRG1 expression through downstream activation of JAK2/STAT3 signaling in cancer cells." (PMID 34930899, 2021). "In cervical cancer, the EMT process of cancer cells was regulated through the JAK2/STAT3 signaling pathway." (PMID 33788424, 2021). "Proliferation, differentiation, and apoptosis of cancer cells were regulated by the Janus kinase 2 (JAK2) signal transduction and activator transcription-3 (STAT3) signaling pathway." (PMID 34641392, 2021). "Future studies will be needed to investigate the role of the JAK2/STAT3 pathway in silencing STING function in human cancers." (PMID 33790360, 2021). "Our in vitro data suggest that the IL-6 and JAK2/STAT3 pathways suppress STING function in cancer cells." (PMID 33790360, 2021). "For the further study, we are trying to examine that rosiglitazone, FDA approved hypoglycemic agent as PPARγ agonists, has anti-cancer activity against RCC through inhibition of JAK2 phosphorylation." (PMID 33917914, 2021).
cancer (continued). "Enhanced cancer cell growth and migration are regulated by the activation of JAK2/STAT3 signaling and activated STAT3 further promotes circ-SOD2 expression through a positive feedback loop." (PMID 34205978, 2021). "It is well known that JAK2/STAT3 signaling pathway is constitutively activated in most primary malignant cancers and its activation rate is positively related with tumor grade." (PMID 33800266, 2021). "It was reported that VEGF-A-induced excessive activation of Janus kinase 2/Signal transducer and activator of transcription 3 (Jak2/STAT3) signaling contributes to the abnormal myeloid cell differentiation in cancer." (PMID 34149730, 2021). "The activation of IL4Rα/IL13Rα1 by IL4/IL13 stimulates JAK1/JAK2/JAK3-STAT6-mediated proliferation of cancer cells." (PMID 33419470, 2021). "Inhibiting JAK2 reduces cell proliferation and induces apoptosis in cancer cells because of inhibition of the phosphorylation of the JAK2 substrates STAT3 and STAT5." (PMID 33503825, 2021). "The association between IL‐6 and JAK2, and STAT3 signalling pathway activation and cancer cell migration was observed in a paracrine or autocrine IL‐6‐rich inflammatory environment." (PMID 33759378, 2021). "In fact, many of these proteins have been shown to have a positive correlation with immune response in cancer, such as Caspase-7, Jak2, NF-kB, and STAT5." (PMID 35047498, 2021). "In different types of human cancers, Jak2/STAT3 signaling is continuously triggered and stimulates tumorigenesis and metastasis by facilitating the expression of cell cycle regulators and angiogenic factors." (PMID 34833950, 2021). "Collectively, our findings indicate that the anti-cancer activity of AT-I in CRC is associated with the induction of apoptosis and suppression of glycolysis in CRC cells, via the disruption of JAK2/STAT3 signaling." (PMID 32273843, 2020). "Among them, IL6 is a well-characterized cytokine that has been reported to be involved in various cancers progression by stimulating JAK2/STAT3 pathway." (PMID 32963220, 2020). "During the progression of cancer, hyperactivation of JAK2/STAT3 signaling results in a poor prognosis." (PMID 32518521, 2020). "The IL-6/JAK2/STAT3 signaling pathway is currently the central object of research on cancer cachexia." (PMID 33158194, 2020). "Accordingly, recent studies show that IL-1β contributes to PC pathogenesis by IL-1 receptor-associated kinase 4 (IRAK4)-mediated activation of NFkB and by triggering the JAK2/STAT signaling in TME, particularly in cancer-associated fibroblasts (CAFs)." (PMID 32659999, 2020). "Inhibited growth and induction of apoptosis through inactivation of JAK2/STAT3 signaling in many cancer cells and tumors have been demonstrated in many published studies." (PMID 33123268, 2020). "It has an essential role in activating JAK2 (janus kinase 2), which causes a persistent STAT3 (signal transducer and activator of transcription 3) activation in cancers." (PMID 32887262, 2020). "In gastric cancer, the proliferation of cancer cells is inhibited by miR-135a via inactivation of JAK2/STAT3 and targeting cyclin D1, Bcl-xl40, kinesin family member C141 and the focal adhesion kinase (FAK) pathway." (PMID 32944391, 2020). "B7-H3 was shown to influence tumor progression by regulating the relative molecules via JAK2/STAT3 pathway in several types of cancer 35-37." (PMID 32398947, 2020). "Napabucasin (BBI608) is an orally bioavailable small molecule known to inhibit cancer stem cells’ activity in the JAK2/STAT3 pathway." (PMID 33158194, 2020). "The IL-6/JAK2/STAT3/MMP-9 pathway has been described in a variety of human cancers and plays an essential role in microvessel proliferation and BM degradation." (PMID 32047820, 2020). "JAK2 is a well-known upstream regulator of STAT3 activation in cancer cells, and the JAK2/STAT3 pathway has been shown to alter the expression of key oncogenes and tumor suppressor genes to enhance the growth, survival, and metastasis of CRC cells." (PMID 32273843, 2020).
cancer (continued). "To confirm that, here we performed a JNK or JAK2 inhibitor test by assessing the anti-cancer effects of pKAL on CD44, Oct 3/4, β-catenin, and MMP-9 as well as the STAT 3 activity of RT-R-MDA-MB-231 cells." (PMID 32326231, 2020). "In this study, we discovered JAK2 to be a key mediator of cancer stemness, and targeting JAK2 successfully ameliorated the persistence of CSCs after RT." (PMID 31511084, 2019). "Previous studies showed that curcumin, the active principle of the Curcuma longa, can suppress JAK2/STAT pathways in different type of cancer and injuries." (PMID 31033209, 2019). "For example, CQ has recently been demonstrated for targeting cancer stem cells through inhibition of Janus kinase 2 (JAK2) signaling pathway." (PMID 31557936, 2019). "JAK2 has a crucial role in cancer cell proliferation and survival, not only via activation of STATs and downstream proteins, but also through inter-pathway cross-talk to activate PI3K/AKT and MEK/ERK signaling." (PMID 31681603, 2019). "The JAK2/STAT3/IL-6 pathway is hyperactivated in several types of cancer and important to the growth of BCSCs." (PMID 31480284, 2019). "We found that LDOC1 deficiency led to reinforcing a reciprocal loop of IL-6/JAK2/STAT3, through which LDOC1 mediates the cancer progression." (PMID 30634502, 2019). "JAK2 is able to modulate cell proliferation by controlling the cell cycle in cancer cells through several diverse mechanisms." (PMID 31817106, 2019). "Several of the key regulators of transcription involved in mesenchymal transformation (e.g., NF-κB, CEBP-β) upregulate under hypoxic conditions in cancer cells, and hypoxia activates the JAK2/STAT5b pathway in several types of cancer." (PMID 30621209, 2019). "Several of these cancers harbour the JAK2 V617F mutant, which drives cell proliferation and can enable immune escape." (PMID 31817106, 2019). "Preclinical studies of targeting STAT3 signaling by STAT3 or JAK2 inhibitors also showed potent antitumor activity in cancers and some of the inhibitors are in clinical trials." (PMID 30755611, 2019). "Accordingly, our novel discovery of CCND2 as a mediator of cancer stemness under JAK2/STAT3 activation provides a rationale for developing JAK2/STAT3 inhibitors to treat intractable cancers." (PMID 31511084, 2019). "Firstly, STAT5 is aberrantly activated in several cancers, and this is often mediated by enhanced JAK2 activation." (PMID 31817106, 2019). "Suppression of TBK1 induces apoptosis of KRAS-driven cancer cells, and JAK2 inhibition of STAT3 activation results in decreased growth." (PMID 30105668, 2019). "We have previously shown that icaritin exhibits anti-proliferative activities both in cancer cells and in cancer-stem cells through the IL-6/Jak2/Stat3 pathway both in vitro and in vivo." (PMID 30922248, 2019). "Recent studies found the JAK2/STAT3 pathway to be another candidate for pharmaceutical agents to limit muscle wasting in experimental cancer cachexia." (PMID 31285507, 2019). "Taken together, our results indicate that JAK2/STAT3/CCND2 signaling contributes to cancer stemness and radioresistance; thus, therapies that specifically target this pathway constitute a biologically driven strategy for enhancing the efficacy of radiotherapy." (PMID 31511084, 2019). "JAK2 is essential for intracellular signaling upon exposure of cancer cells to IFN-γ produced by T cells upon antigen recognition." (PMID 31159869, 2019). "And it has been reported that overexpression of SMC4 activates JAK2/Stat3 and TGFβ/Smad pathway and promotes aggressiveness of cancer cells." (PMID 31871499, 2019). "Herein, we show that MH-mediated inhibition of p-STAT3 in breast (MDA-MB-231) and lung (A549) cancer cell lines is accompanied by decreased levels of gp130 and p-JAK2, two upstream components of the IL-6 receptor (IL-6R) signaling pathway." (PMID 31491838, 2019).
cancer (continued). "Forced or pregnancy-associated JAK2/STAT5 activation lowers the apoptosis anticancer barrier in preexisting early lesions and advances the progression to cancer." (PMID 29778097, 2018). "Remarkably, we found this type of mutation in BRAF, ERBB2, JAK2, and EGFR in cancer genomes, suggesting that the dimerization works as a principal mechanism to regulate the activity of these kinases." (PMID 29930381, 2018). "Lestaurtinib has been reported to be a multi-kinase inhibitor, specifically of the JAK2 signaling pathway; however, many kinase inhibitors have off target effects, making their true anti-cancer mechanism unclear." (PMID 30419054, 2018). "In the present study, we found that Wwox affects the IL-6/JAK2/STAT3 (interleukin-6/Janus kinase-2/signal transducer and activator of transcription-3) axis, inhibiting cancer cell growth and metastasis in a STAT3-dependent manner." (PMID 30154439, 2018). "IFN-γ, secreted by CD4+ T-cells, interacts with its receptors on the cancer cell surface and induces tyrosine phosphorylation of Jak1 and Jak2." (PMID 29796172, 2018). "The variety of the receptors triggering this pathway is unmatched among known signaling cascades, and the wide range of downstream proteins indicate the importance of JAK2/STAT3 axis in cancer progression." (PMID 30109213, 2018). "In the present study, we demonstrated that Wwox impedes the association of JAK2 with STAT3, thereby inhibiting STAT3 phosphorylation and p-STAT3-dependent cancer cell growth in vivo." (PMID 30154439, 2018). "Among the JAK family, JAK2 is an important target for cancer treatment due to its role in cell growth and survival." (PMID 30564118, 2018). "Small molecule inhibitors of ERK1/2 and JAK2 signaling are actively being tested for cancer therapies." (PMID 30038287, 2018). "We noted that JAK2/STAT3, TNF-α, mTOR/p70S6K or mTOR/p/0S6K/4E-BP1, and PI3K/Akt/mTOR signaling pathways associated with melittin in cancers were in accordance with the signaling pathway IDs of hsa04630, hsa04668, hsa04150, and hsa04151." (PMID 29854840, 2018). "JAK2 expression was downregulated in carcinoma tissue (FC 0.82) and SOCS1 expression was slightly upregulated in carcinoma tissue (FC 1.05), although this finding was not statistically significant." (PMID 30603058, 2018). "It has previously been shown that B7-H3 regulates the expression of Bcl-2, Bcl-xL, and Bax via the JAK2/STAT3 signaling pathway to increase the anti-apoptotic ability of cancer cells." (PMID 29088829, 2017). "TM4SF4-triggered OPN expression forms the core for the persistent reinforcement of EMT or cancer stemness by creating a positive feedback autocrine loop with JAK2/STAT3 or FAK/STAT3 pathways." (PMID 29254164, 2017). "We thereby postulate that JAK2 genetic defects (deletion and truncating mutations) in NSCLC represent a likely mechanism underlying the resistance of cancer cells to anti-PD-1/anti-PD-L1 immune checkpoint therapy." (PMID 28977839, 2017). "Evidence suggests that the Janus kinase 2/signal transducer and activator of transcription 3 (Jak2/STAT3) signalling pathway is associated with oncogenesis and the progression and metastasis of different cancers." (PMID 27862996, 2017). "Comparing tumors with and without PD-L1 CNG in 22 cancer types, we found significant mRNA expression changes of PD-L1 in 11 cancer types, of PD-L2 in 9 cancer types and of JAK2 in 15 cancer types." (PMID 29212506, 2017). "Analysis of cancer cell line pharmacogenomic data showed that a high level of JAK2 expression in a panel of NSCLC cell lines is correlated with increased sensitivity to a selective JAK2 inhibitor." (PMID 29082853, 2017). "Examination of TCGA data of 881 cancer cell lines in the cancer cell line encyclopedia (CCLE) cohorts again showed that the IFNγ-IRF1 pathway genetic defects in these cancer cells occurred most often through JAK2 deletion." (PMID 28977839, 2017).
cancer (continued). "Collectively, our findings indicate that TM4SF4-triggered OPN expression is involved in the persistent reinforcement of EMT or cancer stemness by creating a positive feedback autocrine loop with JAK2/STAT3 or FAK/STAT3 pathways." (PMID 29254164, 2017). "Our findings suggested that pantoprazole can alleviate cancer cachexia skeletal muscle wasting by inhibiting the inflammatory response and blocking the JAK2/STAT3 or ubiquitin proteasome pathway." (PMID 28489606, 2017). "IL-6/Janus kinase 2 (Jak-2)/signal transducer and activator of transcription 3 (STAT3) pathway has been implicated as a key player in many cancer types." (PMID 28970500, 2017). "One important mechanism is interfering with the activation of IL-6/Jak-2/STAT3 signalling pathway which was found to have a pivotal role in cancer development and progression." (PMID 28970500, 2017). "A previous study indicated that JAK2/STAT3 was involved in the muscle wasting induced by cancer cachexia by regulating the inflammatory response." (PMID 28489606, 2017). "Then we can draw that TAMs in malignant tumors tend to M2 subtype possibly through CXCL12/CXCR4/JAK2/STAT3 signaling pathway." (PMID 28630636, 2017). "The JAK2/STAT3 pathway regulates not only the anti-apoptotic survival signal but also the motility of cancer cells." (PMID 27012679, 2016). "Combined treatment with a HSP90 inhibitor and a JAK2 inhibitor exert synergistic anti-cancer effects." (PMID 27409672, 2016). "IL-6 is an activator of Jak2/STAT3 signaling pathway which is involved in the development of cancers and EMT." (PMID 27121055, 2016). "Other notable hub genes have also been claimed to be associated with cancers, including MAPK1, MAPK3, JAK2, EGFR, KRAS and NRAS." (PMID 27467251, 2016). "Recently, some evidence has also indicated that HDAC inhibitor suppression of JAK2/STAT3 signaling in cancer cells occurs through inducing the acetylation of histones connected to the promoter of SOCS3, a potent feedback inhibitor of JAK2/STAT signaling." (PMID 26636769, 2015). "They observed that paclitaxel treatment enhanced the expression of cancer stem cell-like markers in surviving cancer cells in vivo and coincided with significant activation of the JAK2/STAT3 pathway." (PMID 26442217, 2015). "Our study also assessed the regulation of signaling molecules implicated in the growth, progression, differentiation, and migration of cancer cells, such as Jak2, STAT5b, insulin-like growth factor-1Rβ, and their phosphorylation status." (PMID 26084564, 2015). "IL-6 contributed to upregulation of genes related to CSCs and cell proliferation as well as activation of JAK2/STAT3 in cancer cells." (PMID 25797257, 2015). "On the other hand, ROS can stimulate the JAK2/STAT3 pathway through the induction of a positive ROS/IL-6/JAK2/STAT3 feedback during starvation-induced autophagy of cancer cells." (PMID 26106584, 2015). "Consistent with our findings, a combination of MEK and JAK2 inhibitors showed remarkable anti-cancer activity in these K-Ras mutant cancer cells." (PMID 25961376, 2015). "Smallmolecule compounds which inhibit aberrant JAK2 activity are beingdeveloped as novel anti‐cancer pharmaceuticals." (PMID 26650445, 2015). "To identify what downstream signals in cancer cells respond to IL-6, we looked at JAK2/STAT3 pathway." (PMID 25797257, 2015). "EBV positive carcinomas show recurrent PIK3CA mutations, extreme DNA hypermethylation, and amplification of JAK2, CD274, and PDCD1LG2." (PMID 25859432, 2015). "JAK2 is known to play a significant role in hematopoiesis and immune responses, and is often involved in cytokine dependent cancers." (PMID 24830942, 2014). "Knockdown of MUC16 inhibits in vitro and in vivo proliferation of cancer cells MUC16-triggered activation of STAT3 via JAK2 results in increasing cancer cell proliferation." (PMID 24886523, 2014).